ENSG00000269403 (novel protein)
Gene: Protein-coding gene on chromosome 19 (51,350,373 to 51,368,099, reverse strand). Ensembl gene ENSG00000269403.
Genetic constraint (gnomAD): Missense variants: 65 observed, 61.52 expected, observed/expected ratio (o/e) 1.06, 90% interval 0.86 to 1.3. Synonymous variants: 35 observed, 25.45 expected, observed/expected ratio (o/e) 1.38, 90% interval 1.05 to 1.79.